NXF5 (nuclear RNA export factor 5)
Description:
Could be involved in the export of mRNA from the nucleus to the cytoplasm. Could also have a role in polarized cytoplasmic transport and localization of mRNA in neurons.
Gene: Transcribed unprocessed pseudogene on chromosome X (101,832,537 to 101,843,278, reverse strand). Ensembl gene ENSG00000126952.
Subcellular location: Cytoplasm; Nucleus
Diseases named in the same sentence as NXF5 in open-access papers:
NXF5 is named in the same sentence as 11 diseases in open-access papers, as found by Europe PMC text mining. Sharing a sentence is not in itself a finding about the gene and the disease. The quoted sentences say what the papers report.
Intellectual disability (3 papers, 2005 to 2024). "We previously reported on the loss of NXF5 in a male patient with a syndromic form of intellectual disability." (PMID 23675524, 2013). "NXF5 has been linked to intellectual disability and is known to be involved in brain development." (PMID 39231932, 2024).
Anxiety (1 paper, 2013). Intense feelings of nervousness, tension, or panic often arise in response to interpersonal stresses. "This patient, who thus lacks the NXF5 gene, shows several prominent clinical characteristics that include severe ID, muscular wasting, anxiety with eye contact avoidance, and poor adaptive functioning." (PMID 23675524, 2013).
Cognitive impairment (1 paper, 2013). Abnormal cognition is characterized by deficits in thinking, reasoning, or remembering. "Based on morphological, histological, molecular and behavioural analyses of these Nxf7 KO mice, we provide strong evidence that Nxf7 is the functional equivalent of NXF5 and that dysfunction of NXF5 could relate to cognitive impairment." (PMID 23675524, 2013).
fragile X syndrome (1 paper, 2013). A genetic syndrome caused by mutations in the FMR1 gene which is responsible for the expression of the fragile X mental retardation 1 protein. "Therefore, next to FMRP for which its absence results in Fragile-X syndrome, NXF5 seems to be a second ID-related protein involved in mRNA metabolism in neurons." (PMID 23675524, 2013).
Primary amenorrhea (1 paper, 2020). "A cytogenetic analysis in a patient presenting with delay of puberty and primary amenorrhea, and no other clinical features showed a de novo translocation 46,XX, t(X;15)(Xq22;p11) with a breakpoint interval containing the NXF5 gene." (PMID 33095795, 2020).
X-linked intellectual disabilities (1 paper, 2025). "The role of NXF5 CNVs in X-linked intellectual disabilities (XLID), potentially with syndromic features, has been considered “highly questionable” due to the scarcity of reported cases with ID." (PMID 40428393, 2025).
neurodevelopmental disorder (1 paper, 2025). A behavioral and cognitive disorder with onset during the developmental period that involves impaired or aberrant development of intellectual, motor, or social functions. "Given these considerations, this report highlights the potential role of NXF5 CNVs as a candidate factor in XLID with ASD features, warranting further investigation, also regarding the sex-specific expression of the neurodevelopmental disorder." (PMID 40428393, 2025).
NXF5 also shares sentences with these, for which no sentence is quoted: language delay (1 paper); microcephaly (1); ovarian failure (1); personality disorder (1).